S100A9 (S100 calcium binding protein A9)
Diseases named in the same sentence as S100A9 in open-access papers (continued):
Sharing a sentence is not in itself a finding about the gene and the disease.
Obesity (28 papers, 2013 to 2026). Accumulation of substantial excess body fat. "Certain S100 proteins, namely S100A4, S100A8/S100A9 heterodimer, and S100B, have been implicated in the pathophysiology of obesity-promoting macrophage-based inflammation via toll-like receptor 4 and/or receptor for advanced glycation end-products ligation." (PMID 35328627, 2022). "In parallel, blocking S100A9 normalize skin inflammation in these mice underlining a pathogenic role of S100A9 overexpression in the obesity-associated amplification of skin inflammation." (PMID 35198063, 2022). "Improvement of skin inflammation and wound repair upon reduction of S100A9 by pharmacological inhibition or by reduction of SFA uncovers the pathogenic role of S100A9 overexpression in obesity." (PMID 35198063, 2022). "To elucidate the cellular sources and underlying mechanisms of amplified S100A9 expression in inflammation and repair processes in conditions of obesity we analyzed S100A9 expression in our skin inflammation and skin wound healing models." (PMID 35198063, 2022). "We reveal a yet unrecognized impact of obesity-associated S100A9 overexpression on macrophage differentiation." (PMID 35198063, 2022). "Certain S100 proteins including S100A8 and S100A9 have been associated with pathophysiological processes in obesity." (PMID 35198063, 2022). "Of note, we observed a similar dysregulation of S100A8 and S100A9 and M2-like macrophage markers as in the obesity-associated skin inflammation model." (PMID 35198063, 2022). "Our study revealed that elevated levels of S100A8/S100A9 were closely associated with the development of obesity, while hypomethylation of the promoter region resulted in upregulation of S100A8/S100A9 expression." (PMID 34055926, 2021). "Key predictive proteins such as C9, TTR, CRP, and S100A9 are not only differentially abundant in obesity but also implicated in the pathogenesis of endothelial dysfunction, systemic inflammation, and insulin resistance, further validating their mechanistic relevance." (PMID 40981199, 2025). "In the present study we explore the mechanisms of obesity-associated overexpression of S100A9." (PMID 35198063, 2022). "Consequently, inhibition of S100A9 restores disturbed M2-like macrophage differentiation in mouse models of obesity-associated skin inflammation and wound repair." (PMID 35198063, 2022). "Since M1/M2 transition is a crucial step during tissue repair we compared S100A8 and S100A9 during skin wound healing in wildtype mice and in db/db mice, the latter representing an established model of obesity-associated impaired wound healing with disturbed macrophage differentiation." (PMID 35198063, 2022). "However, underlying mechanisms of S100A9 overexpression in obese conditions and its pathogenic role in obesity-mediated exacerbation of skin inflammation and dysregulated macrophage differentiation are still unknown." (PMID 35198063, 2022). "The expression of calprotectin subunit S100A9 is increased in people with obesity in whom it promotes inflammation in the epicardial fat40." (PMID 38273044, 2024). "Enriching immune-related proteins, such as S100A9 andhaptoglobin, underscores the role of inflammation in obesity." (PMID 40230956, 2024). "In this PPI interaction, S100A9 is expressed when obesity triggers cellular defencemechanisms and response to microbial stimuli to combat oxidative damage and inflammation." (PMID 40230956, 2024). "We therefore supposed an indirect mechanism of S100A9 overexpression during inflammation in obesity that is mediated by macrophages as one important source of TNFα and IL-1β." (PMID 35198063, 2022). "In conclusion, our data indicate that a dysregulated S100A9 overexpression as observed in obesity has detrimental effects on macrophage differentiation and thus on inflammation and tissue repair." (PMID 35198063, 2022).
Obesity (continued). "It further indicates that in conditions of obesity the activation state of adipocytes in the dWAT is changed resulting in the expression of S100A9 in inflammatory settings." (PMID 35198063, 2022). "S100A9 overexpression in obesity impaired macrophage differentiation via TLR4-NFkB signaling, worsening inflammation and wound healing." (PMID 35935235, 2022). "This demonstrates the functional role of SFA to the overexpression of S100A9 in skin inflammation in obesity." (PMID 35198063, 2022). "The fact that obesity-associated mediators do not induce S100A9 expression but TNFα and IL-1β do so, suggests an indirect mechanism for the increased S100A9 induction in dWAT and epidermis in the inflamed skin in obesity." (PMID 35198063, 2022). "Next, we investigated the link between impaired M1 to M2 transition and pathological S100A9 overexpression in obesity-mediated impaired tissue repair using the db/db mouse model of delayed wound healing." (PMID 35198063, 2022). "Similar to the results obtained during the development of obesity, the reduced expression of Il33 and Penk in the epiWAT of Gipr-/- BM mice was restored to WT BM control levels in Gipr-/-S100a9-/-BM mice." (PMID 33717200, 2021). "One study found that in obese individuals, the methylation levels of the S100A8 and S100A9 genes exhibit a negative correlation with their expression levels, which is closely associated with the pathological mechanisms underlying obesity." (PMID 40702573, 2025). "Furthermore, in the context of obesity, S100a8/S100a9, which are significant hysteresis genes recognized as damage-associated molecular patterns (DAMPs), are presumed to trigger ATM-mediated immune responses." (PMID 38173717, 2023). "S100A9 attenuates the development of M2 and induces pro-inflammatory functions in obesity." (PMID 37533789, 2023). "In our previous study, we observed an increase of S100A9 during skin inflammation in obesity." (PMID 35198063, 2022). "In conditions of obesity this induction of S100A9 is highly increased in both skin departments." (PMID 35198063, 2022). "However, in the presence of high SFA levels, like they are present in obesity, S100A9 induces an inflammasome-dependent secretion of IL-1β by monocytes and macrophages as shown here for both mouse peritoneal macrophages and human monocytes." (PMID 35198063, 2022). "Restoration of M2-like macrophage activation upon blocking of S100A9 in enhanced obesity-associated skin inflammation in obese mice and short-HFD mice and impaired wound healing in db/db mice prove the novel role of S100A9 in the control of macrophage polarization." (PMID 35198063, 2022). "Consistent with studies showing high expression of S100A9 in keratinocytes in psoriatic skin lesions and in wounds 35,37, we found high epidermal S100A9 expression in skin inflammation and during wound healing in our mice that is further exacerbated by obesity." (PMID 35198063, 2022). "Consequently, inhibition of S100A9 or reduction of SFA as one driver of S100A9 overexpression in obesity breaks this viscous cycle of S100A9 overexpression." (PMID 35198063, 2022). "Understanding the mechanisms of obesity-driven S100A9 overexpression might open new opportunities to interfere with dysregulated inflammation and tissue repair in obesity." (PMID 35198063, 2022). "In summary, in obesity overexpression of S100A9 impairs appropriate macrophage activation and polarization preventing resolution of skin inflammation that finally contributes to a sustained and amplified skin inflammation and impaired tissue repair in obesity." (PMID 35198063, 2022). "We show that SFA, which are increased in obesity, together with S100A9, an early danger molecule, induce IL-1β release in macrophages which in turn amplifies S100A9 expression initiating a vicious cycle of sustained S100A9 overexpression in skin inflammation in obesity." (PMID 35198063, 2022).
Obesity (continued). "Since our data indicate that SFA are one important driver of S100A9 overexpression in obesity we investigated whether reduction of SFA restores M2 differentiation." (PMID 35198063, 2022). "We reveal a yet unrecognized impact of S100A9 on M2-like macrophage differentiation contributing to disturbed macrophage polarization and subsequent impaired resolution of skin inflammation and tissue repair in obesity." (PMID 35198063, 2022). "We found that the high expression of S100A8 and S100A9 was related to obesity." (PMID 34055926, 2021). "In addition, increased gene expression of S100A8 and S100A9 in visceral AT and increased concentrations of S100A8/A9 complexes in the circulation have been observed in obese patients and correlated with the obesity associated low-grade inflammation in the patients." (PMID 35198063, 2022). "We selected five of these (ACACA, CETP, CTGF, S100A8, S100A9) for further analyses based on reported adipose or adipocyte gene expression changes in response to weight loss/dietary intervention (ACACA, CETP, CTGF), and/or associations with obesity or related traits (GWAS, and/or other literature)." (PMID 25651499, 2015). "In a previous study, investigating mechanisms of increased skin inflammation in mouse models of obesity including db/db mice, we described an increased and prolonged expression of the alarmins, S100A8 and S100A9, during diabetic wound healing in db/db mice." (PMID 39337466, 2024). "Quantification of immunofluorescent staining of recently recruited (CD68+S100A9+) myeloid cells did not reveal any significant differences in monocyte recruitment between lean individuals and individuals with obesity." (PMID 37414931, 2023). "Typical obesity-associated mediators such as high SFA, glucose or insulin do not directly change S100A9 expression in keratinocytes and the dWAT." (PMID 35198063, 2022). "In the present study we found almost no expression of S100A9 in skin of lean, obese and db/db mice suggesting that obesity per se does not affect S100A9 expression." (PMID 35198063, 2022). "IL-1β and TNFα were identified as inducers of S100A9 in epidermis and dWAT while obesity-associated factors such as high glucose, insulin or SFA do not affect S100A9 expression." (PMID 35198063, 2022).
pancreatic cancer (28 papers, 2012 to 2026). "Only one study has reported that S100a9 as a potential pathogenic factor for pancreatic cancer–induced cachexia in vitro." (PMID 39911133, 2025). "The S100A8/S100A9 secreted by monocytes regulated the behavior of pancreatic cancer cells by causing a pre-metastasis cascade related to cancer spread." (PMID 35651786, 2022). "The main effects of S100a9 in pancreatic cancer are the inhibition of NF-κB and the stimulation of mTOR, which inhibit autophagy." (PMID 37723445, 2023). "In summary, we demonstrate that CD74 regulates the expression and secretion of S100A8 and S100A9 and that these cytokines are clear prognostic markers in pancreatic cancer." (PMID 37629174, 2023). "In this study, we found that PSCs stimulate pancreatic cancer cells to secrete S100A9, which initiates the attraction of circulatory monocytes into cancer tissue." (PMID 34374812, 2022). "The protein level of S100A9 in pancreatic cancer cell lines was also increased when the cells were cocultured with PSCs in the coculture system." (PMID 34374812, 2022). "We next investigated downstream mediators of S100A8 and S100A9 signalling in pancreatic cancer cells, including phospho-MAPK proteins and NF-κB." (PMID 30558665, 2018). "We also reported that exogenously added S100A8 and S100A9 proteins enhanced the migration and proliferation of colorectal and pancreatic cancer cells in culture." (PMID 30558665, 2018). "In the current study, we found that S100A8 and S100A9 proteins influenced cytokine secretion from pancreatic cancer cells in overlapping but also distinct ways." (PMID 30558665, 2018). "Our findings, together with other studies in pancreatic cancer tissue, saliva, and serum suggest that the upregulation of S100A9 DAMP signal is a common and valid biomarker of inflammatory processes and immune response." (PMID 31448371, 2016). "Therefore, this study involves the identification of various overexpressed protein members of the S100 protein family, including S100-A4, S100-A6, S100-A8, S100-A9, and S100-A11, to develop a successful multiepitope-based vaccine against pancreatic cancer." (PMID 38976715, 2024). "We then investigated whether S100A8 and S100A9 could function as prognostic markers of pancreatic cancer." (PMID 37629174, 2023). "However, in pancreatic cancer cells, the main effects of S100a9 are the inhibition of NF-κB and stimulation of mTOR, both of which inhibit autophagy." (PMID 37723445, 2023). "In summary, in this study, we demonstrate that the secretion of S100A9 is not only limited to myeloid cells and may also be induced in pancreatic cancer cells incubated with PSCs." (PMID 34374812, 2022). "We found that the secretion of S100A9 could be enhanced in pancreatic cancer cells when they were incubated with PSCs and that S100A9 acts as a chemoattractant to recruit monocytes." (PMID 34374812, 2022). "According to the analyses of the two microarray datasets, we hypothesized that PSCs might stimulate pancreatic cancer cells to secrete S100A9 and influence the progression of pancreatic cancer." (PMID 34374812, 2022). "Moreover, genome-wide expression profiling of JHDM1D-AS1 expressing pancreatic cancer cells in mouse tumor xenografts showed increased expression of inflammatory response genes S100a8 (or Mrp8) and S100a9 (or Mrp14)." (PMID 35903199, 2022). "For instance, S100A8 and S100A9 enhance the production of IL-8 in pancreatic tumor cells, which could promote the accumulation of immunosuppressive myeloid cells, including MDSCs." (PMID 34187428, 2021). "However little is known about S100A8 and S100A9-mediated cross talk between stromal monocytes and pancreatic cancer cells." (PMID 30558665, 2018).
pancreatic cancer (continued). "Therefore, we aimed to determine whether the secretion of S100A9 from pancreatic cancer cells induced by PSCs could induce the migration of monocytes." (PMID 34374812, 2022). "Overall, our study provides valuable insights into the critical role of CD74 in regulating the oncogenic properties of pancreatic cancer cells and its influence on the expression and secretion of S100A8 and S100A9." (PMID 37629174, 2023). "Our observation that S100A8 and S100A9 transcripts were detected in the eight cancer cell lines, and not in the HPNE control cell line, suggests that these two S100s also act directly on pancreatic cancer cells." (PMID 37627239, 2023). "Pancreatic cancer cells stimulated by S100A8 and S100A9 increased the secretion of pro-inflammatory cytokines IL-8, TNF-α and FGF." (PMID 35651786, 2022). "The proteins S100A9 and S100A8 are involved in a paracrine feedback loop between pancreatic cancer cells and monocytes." (PMID 35646116, 2022). "Stimulation of cultured pancreatic cancer cells with S100A8 and S100A9 increased the secretion of the pro-inflammatory cytokines IL-8, TNF-α, and FGF." (PMID 30558665, 2018). "In the current study, we show that exposing monocytes to pancreatic tumour cell-derived conditioned media increased the expression of both S100A8 and S100A9." (PMID 30558665, 2018). "We previously showed that the stromal compartment of colorectal and pancreatic cancers contain CD14+ monocytic cells expressing S100A8 and S100A9 proteins." (PMID 30558665, 2018). "The other study revealed that the ratio of S100A9- and S100A8- positive cells in the stroma was affected by the status of tumor suppressor protein Smad4 in corresponding pancreatic cancer cells." (PMID 22838504, 2012). "S100A8 and S100A9 activated MAPK and NF-κB signalling in pancreatic cancer." (PMID 30558665, 2018). "Conversely, pancreatic cancer cell-derived conditioned media and the individual cytokines, TNF-α and TGF-β induced the expression of S100A8 and S100A9 proteins in the HL-60 monocytic cell line and primary human monocytes, while FGF and IL-8 induced the expression of S100A9 only." (PMID 30558665, 2018). "We report here a RAGE-dependent increase in levels of phosphor-Erk1/Erk2 and phospho-p38 phosphorylation following S100A8 and S100A9 treatment of pancreatic cancer cells, although we did not examine the basal levels of these proteins." (PMID 30558665, 2018). "A previous proteomics analysis reported that S100A9 protein was detected in 44% of urine samples, but not in plasma, of pancreatic cancer patients 6, which indicates that urine proteomics might provide tumor-specific biomarkers for pancreatic cancer." (PMID 38902359, 2024). "Further endpoints were to assess whether pancreatic cancer cells are able to expand MDSCs in vitro and to evaluate the role of the inhibitory co-stimulatory molecules PDL1 and CTLA4 searching also for any potential effect of the S100A8 and S100A9 molecules." (PMID 23359812, 2013). "The proliferation of the four studied pancreatic cancer cell lines was not influenced by S100A8, S100A9, S100A8/A9 and/or TGFβ1." (PMID 24670043, 2014). "Of note, our group has previously identified S100A9 to be synergistically regulated by cooperative Hedgehog-EGFR signaling, suggesting a possible role in Hedgehog-dependent malignancies including nonmelanoma skin cancer and pancreatic cancer." (PMID 32503348, 2020).
inflammatory bowel disease (27 papers, 2011 to 2025). A spectrum of small and large bowel inflammatory diseases of unknown etiology. "Calprotectin, a dimer of the calcium-binding proteins S100A8 and S100A9, is highly represented in neutrophils, and levels in feces are known to reflect disease activity in other inflammatory bowel diseases." (PMID 31172380, 2019). "S100A8 and S100A9 are known to have proinflammatory functions and are expressed in many diseases like inflammatory arthritis and inflammatory bowel diseases but also they are expressed in several types of cancer such as lung, colorectal, and liver cancer." (PMID 26273651, 2015). "Often forming heterodimers, S100A8 and S100A9 serve as biomarkers for the diagnosis and therapeutic responses in inflammatory diseases like inflammatory arthritis and inflammatory bowel disease, while blocking their activity resulted in reduced inflammation in mouse models." (PMID 36259488, 2022). "The combination of epigenetics and transcriptomics revealed that the S100A9 gene in the gut of inflammatory bowel disease (IBD) patients is characterized by high DNA methylation and low RNA expression, and was identified as a new diagnostic marker." (PMID 38814387, 2025). "Calcium-binding proteins S100A8 and S100A9, which belong to the S100 protein family and are involved in anti-infective and proinflammatory responses in the form of S100A8/S100A9 heterodimers, are viewed as the alarmins and biomarkers of inflammatory bowel disease." (PMID 35658572, 2022). "Also, serum levels of S100A8/S100A9 showed their utility in monitoring the presence of inflammation in patients with Crohn’s disease or ulcerative colitis, and S100A12 concentrations in the serum of patients with inflammatory bowel disease are correlated with disease activity." (PMID 37627347, 2023).